CASP9 (caspase 9)
Diseases named in the same sentence as CASP9 in open-access papers (continued):
Sharing a sentence is not in itself a finding about the gene and the disease.
cardiac hypertrophy (4 papers, 2012 to 2022). "Similar to the findings in chronic intermittent hypoxia, FOXO1 induces upregulated expression of an apoptosis-related gene (Bim) and caspase 9, leading to cardiac hypertrophy in obstructive sleep apnea syndrome." (PMID 34820440, 2021). "There are evidence-based studies suggesting the role of caspase 3 and caspase 9 in both cellular and animal models of cardiac hypertrophy." (PMID 32617142, 2020). "Since Caspase 9 is one of the key components of the intrinsic apoptotic pathway, its down regulation implies possible interference in the basic apoptotic signaling induced by the deficiency of PPAR α as similar results were observed in both the cardiac hypertrophy models." (PMID 35224041, 2022).
chronic kidney disease (4 papers, 2021 to 2024). Impairment of the renal function secondary to chronic kidney damage persisting for three or more months. "Our starting point in the present study was the assumption that caspase-9, recently identified as a hotspot for SNPs in the genomes of chronic kidney disease patients, may be involved in ferroptosis." (PMID 38489367, 2024). "Furocoumarins are one of the most promising agents in the alleviation of oxidative and inflammatory stress-induced pathophysiological morbidities including chronic kidney disease due to their ability to regulate the activity of CASP-3, CASP-8, CASP-9, and SOD." (PMID 38660689, 2024).
chronic myeloid leukemia (4 papers, 2019 to 2024). "In other cancer cells, namely, chronic myeloid leukemia cells, NaB was found to induce apoptosis via the activation of caspase 8 and caspase 9, which are key mediators of the extrinsic and intrinsic apoptotic pathways, respectively." (PMID 39200243, 2024). "It has been reported that genetic and pharmacological inhibition of Serpine1 led to apoptosis mainly mediated by caspase-9 activation in chronic myeloid leukemia CD34 cells." (PMID 39308919, 2024).
endometriosis (4 papers, 2013 to 2025). The growth of functional endometrial tissue in anatomic sites outside the uterine body. "In summary, this study has systematically investigated the expression profiles of PGC-1α, ERRα, ERβ, IL-6, caspase-3, and caspase-9 in endometriosis tissues and their effects on endometrial stromal cells." (PMID 39822256, 2025). "Lastly, this study found that caspase-9 expression was greatly reduced, which strongly suggests that the endogenous apoptotic mechanism of endometriosis was significantly hindered." (PMID 39822256, 2025). "We also found that MIS treatment induces caspase 9 cleave in Western blots, providing another line of evidence that MIS treatment induces apoptosis in endometriosis cells." (PMID 23853725, 2013). "By inhibiting the activation of caspase-3 and caspase-9, the overexpression of PGC-1α may reduce the amount of cell apoptosis and provide favorable conditions for the evolution of endometriosis illness." (PMID 39822256, 2025). "In addition, rutin, one of the flavonoids of Codium fragile, inhibited apoptosis by regulating the expression of BCl-2/BAX ratio, Caspase-9, and cleaved poly ADP-ribose polymerase (PARP) in endometriosis development in a rat model." (PMID 37760047, 2023).
epidermoid carcinoma (4 papers, 2014 to 2025). "Meanwhile, in squamous cell carcinoma tissue, Bcl-2 expression was higher, while the Caspase-3, Caspase-9 and Bax were significantly decreased." (PMID 31666604, 2019).
epilepsy (4 papers, 2020 to 2022). A brain disorder characterized by episodes of abnormally increased neuronal discharge resulting in transient episodes of sensory or motor neurological dysfunction, or psychic dysfunction. "A study has confirmed that epilepsy can induce hippocampal apoptosis, high expression of caspase 3 and caspase 9, ROS, mitochondrial depolarization, and increased intracellular calcium concentration." (PMID 32337274, 2020). "Accompanied by the release of cytochrome C into cytosol, caspase 9 increased obviously in refractory epilepsy neurons with the gain function of VDAC1 (117.6 ± 1.75%, P < 0.05) and decreased in refractory epilepsy neurons with the loss function of VDAC1 (84.7 ± 2.66%, P < 0.05)." (PMID 33336032, 2020). "In this part, we could see that Bcl-2 inhibited the cell apoptosis, release of cytochrome C, and activation of caspase 9 in epilepsy, which could be strengthened by VDAC1 downregulation." (PMID 33336032, 2020). "Therefore, Bax induced the cell apoptosis, release of cytochrome C, and increase of caspase 9 in epilepsy, which could be inhibited by VDAC1 downregulation." (PMID 33336032, 2020). "The expression levels of proapoptotic proteins, including C-caspase 3, C-caspase 9, and Bax, in the hippocampus of normal mice were low, while these proteins were significantly upregulated in PTZ-induced epilepsy mice." (PMID 34336105, 2021).
esophageal squamous cell carcinoma (4 papers, 2022 to 2026). Esophageal squamous cell carcinoma (ESCC) is a type of esophageal carcinoma (EC) that can affect any part of the esophagus, but is usually located in the upper or middle third. "HECTD3 promotes esophageal squamous cell carcinoma (ESCC) growth and cell survival by suppressing Caspase-9 activation." (PMID 39487119, 2024).
fibrosis (4 papers, 2014 to 2024). the formation of excess fibrous connective tissue in an organ or tissue in a reparative or reactive process. "The expression levels of CASP9 in the kidney were shown to correlate with fibrosis severity in FA and UUO fibrosis models and were used as a kidney disease risk gene." (PMID 38343546, 2024). "Most notably, up-regulation of caspase-9 and epithelial membrane protein 1 (EMP1) was associated with fibrosis and Bcl-2-related proline-rich protein (BCL2L12) and programmed cell death protein 1 precursor (PDCD1) was associated with cirrhosis." (PMID 27280444, 2016).
gastric adenocarcinoma (4 papers, 2018 to 2022). "The down-regulation of Bcl-2 and up-regulation of Bax, Caspase-9, and Caspase-3 protein expression in cancerous cells may draw attention to thymol as a potential candidate for the development of future gastric adenocarcinomas treatment strategies." (PMID 32709059, 2020). "In an in vitro experimental settings, phytol has been demonstrated to induce apoptosis in human gastric adenocarcinoma AGS cells, downregulates Bcl-2, upregulates Bax, activates caspase-9 and -3 and induces PARP cleavage." (PMID 30100991, 2018).
heart failure (4 papers, 2022 to 2025). Inability of the heart to pump blood at an adequate rate to meet tissue metabolic requirements. "miR-30e negatively regulates LOX1 expression, inhibits NF-κB p65/Caspase-9 signaling, reducing apoptosis and fibrosis, protecting heart function post-MI, and improving heart failure in rats." (PMID 40642081, 2025). "The treatment also regulated apoptosis-related protein expression, partially reversing the increase in cleaved Caspase-9, cleaved Caspase-3, and Bax and the suppression of Bcl-2 observed in the heart failure rats." (PMID 39605071, 2024). "The present study showed that H2S significantly decreased ac-PGC-1α levels and cleaved caspase-9 in heart failure." (PMID 36757027, 2023).
hyperhomocysteinemia (4 papers, 2013 to 2022). A serious metabolic condition caused by mutations in the MTHFR gene, medications, or nutritional deficiency. "Furthermore, melatonin treatment diminished cytochrome c release from mitochondria and reduced caspase 3 and caspase 9 activation induced by hyperhomocysteinemia in neuronal cells." (PMID 32651992, 2020).
injury (4 papers, 2016 to 2024). Damage inflicted on the body as the direct or indirect result of an external force, with or without disruption of structural continuity. "In a rat model of blunt ocular trauma, treatment with a highly selective caspase-9 inhibitor, Pen1-XBir3, reduces neuronal death and improves retinal function, supporting the role of caspase-9 in mediating neuronal death in an acute trauma model." (PMID 34305609, 2021). "Here, we initially demonstrated the beneficial role of caspase-9-dependent autophagy in acute liver injury." (PMID 27580936, 2016). "In summary, this study presented the possible beneficial role of caspase-9 in autophagic process in CCl4-triggered acute liver injury." (PMID 27580936, 2016). "The difference in the expression of caspase 9 and caspase 3 in lead-induced nerve injury suggested other factors might affect the expression of caspase 3 during this process." (PMID 26683706, 2016).
meningioma (4 papers, 2010 to 2023). A generally slow growing tumor attached to the dura mater. "High-grade meningioma shows higher levels of active AKT, and its phosphorylation inhibits proapoptotic factors like Bad, Bax, caspase-9, and forkhead, thereby inhibiting apoptosis." (PMID 37887327, 2023). "Regarding downstream gene cascades of Akt, apoptosis-induced genes including CASP9 (3.78-fold), CDKN1A (8.64-fold), AXIN2 (2.78-fold), APC2 (3.12-fold), and EP300 (5.35-fold) were detected with significant down-regulation in fibroblastic meningiomas." (PMID 23285163, 2012).
oral squamous cell carcinoma (4 papers, 2006 to 2022). "A later study, focusing on oral squamous cell carcinoma, indicated that treatment of cancer cells with aloe-emodin significantly upregulated the expression of caspase-9 and caspase-3 and induced apoptosis." (PMID 36193154, 2022). "Consistently, lycorine treatment decreased the relative levels of caspse-3, caspase-9 and PARP in HSFs, which may reflect an increase in the degradation of Caspse9, Caspase3 and PARP, similar to that in oral squamous cell carcinoma HSC-3 cells." (PMID 35685086, 2022).
schizophrenia (4 papers, 2022 to 2026). A major psychotic disorder characterized by abnormalities in the perception or expression of reality. "Conversely, other TNFSF downstream mRNAs were unchanged (BAX, BID, CASP1, CASP3, CASP8, and CASP9) in high-inflammation schizophrenia cases compared with low-inflammation controls." (PMID 41567988, 2026). "Our results suggest significant relationships between the increased expression of apoptosis genes (Bcl2, Birc6, Bax, Casp3, and Casp9) in peripheral blood lymphocytes and immune system dysregulation in patients with schizophrenia." (PMID 35566680, 2022). "Similarly, the caspase pathway, fundamental for apoptosis, is overactivated in schizophrenia, as the caspase-3 and caspase-9 gene expression serum levels were significantly increased in patients with schizophrenia." (PMID 41303622, 2025).
skin tumors (4 papers, 2009 to 2025). "When compared with ST which contains one additional hydroxyl group, ST increased the expression of caspase-9 in both chemical- and UVB-induced skin tumor mouse models." (PMID 19597578, 2009).
ZIKV infection (4 papers, 2021 to 2025). "As expected, ZIKV infection triggered the activation of both caspase-8 and caspase-9, revealing the fact that various biological processes are triggered during ZIKV infection." (PMID 35972780, 2022). "To delineate the molecular mechanism by which cellular pyroptosis was instigated under ZIKV infection, we detected the activation of caspase-8 and caspase-9 in infected JEG-3 cells by the Western blot analysis." (PMID 35972780, 2022). "Results showed that the specific cleavage forms of active caspase 7 and caspase 9 were detected in cells infected with ZIKV on 1 day and 2 day post infection, implying the induction of ER stress mediated intrinsic apoptosis in response to ZIKV infection." (PMID 33432092, 2021). "Another previous study has recently reported that ZIKV infection triggers the intrinsic apoptotic pathway in SH-SY5Y cells with changes in mitochondrial membrane potential, cytochrome c release, and caspase-9 activation, and that proapoptotic protein Bax plays a central role in this process." (PMID 34834918, 2021).
asthma (3 papers, 2014 to 2025). "Consistently, caspase-9 activity in the testis of asthma mice was significantly higher than that of the control group." (PMID 26938720, 2016). "Conclusively, the present study demonstrates that asthma could induce apoptosis in testis tissue possibly through the mitochondrial pathway, in which caspase-9, caspase-3 and PARP are significantly activated." (PMID 26938720, 2016). "Despite these limitations, our study identifies seven core targets (HSP90AB1, CCNB1, CCK, CDK6, CASP9, NR3C1, and ERBB2) that offer promising avenues for developing novel asthma therapies." (PMID 41403444, 2025). "DNA ladder and immunochemistry showed significant increase in apoptotic index of the asthmatic testis, whereas a decrease in mRNA expression of Bcl-2 and increases in Bax, BNIP3, caspase-9, and AIF were observed in the asthma group." (PMID 26938720, 2016). "Consistent with the PCR array data, the transcriptional expression of Bcl-2, an anti-apoptosis factor, was markedly decreased in the testis of asthma mice, while the mRNA transcription of pro-apoptosis genes including Bax, BNIP3, caspase-9 and AIF were enhanced significantly in asthmatic testis." (PMID 26938720, 2016).
brain tumor (3 papers, 2007 to 2018). "Associations have been suggested for LFS-associated brain tumors with nonsense PVs in CASP9 (caspase-9), for a POT1 (protection of telomeres 1) missense variant with cardiac and breast angiosarcomas, and for CDKN2A PVs with hereditary sarcoma cases." (PMID 30086788, 2018).
breast adenocarcinoma (3 papers, 2015 to 2025). "Selenium also increases mitochondrial caspase-9 activation which promotes apoptosis and produces synergistic levels of anti-neoplastic cytotoxicity in combination with anthracyclines (e.g. mammary adenocarcinoma MCF7 cell type)." (PMID 25821636, 2015).
co-infection (3 papers, 2002 to 2025). "This study demonstrates that piscine HNF4α contributes to host antibacterial and antiviral defense by inducing the expression and activities of caspase 3 and caspase 9, positioning it as a potential therapeutic target for bacterial, viral, and coinfection scenarios." (PMID 40920830, 2025). "Blocking activation of Caspase-9 by Caspase-9 inhibitor Z-LEHD-FMK (BioVison, 40 uM) inhibited apoptosis induction by co-infection with VV-miR-34a and VV-Smac." (PMID 27552933, 2016). "The percentage of cells with fragmented DNA induced by co-infection of Adv-Bax, Adv-APAF1 and Adv-Casp9 in U251 cells was only 0.6% (lower second left panel)." (PMID 11870542, 2002).
colorectal adenocarcinoma (3 papers, 2018 to 2020). The most common type of colorectal carcinoma. "The present study outlines the potential of AC for CRC treatment, as this extract induced cytotoxicity of human colorectal adenocarcinoma HT-29 cells, which was accompanied by increases in apoptotic cells and ROS formation; a reduction in MMP; and increases in caspase-9 and 3 activities." (PMID 32204339, 2020).
depression (3 papers, 2024 to 2026). "Behavioral and reproductive assessments included depression-like behavior tests, sexual behavior, sperm quality, testicular histopathology, steroidogenesis proteins (AR, CYP11A1, StAR), and apoptosis markers (Hsp70, caspase-3, caspase-9)." (PMID 41598271, 2026). "The downstream of PI3K/AKT pathway includes caspase 9 (CASP9), glycogen synthase kinase 3 (GSK3), protein 21 (P21), mammalian target of rapamycin (mTOR), and other pathways, which have been widely reported to play a regulatory role in inflammatory response, depression, and cancer development." (PMID 39723076, 2024).
diabetic nephropathy (3 papers, 2014 to 2020). "To determine the protective effect of DP extract on diabetic nephropathy, we measured the expression of Bax, cleaved-caspase 3, and cleaved-caspase 9, which are upregulated in the kidney of diabetic rats, promoting apoptotic cell death." (PMID 31963869, 2020).
diabetic retinopathy (3 papers, 2017 to 2022). "Down-regulates caspase-3, caspase-9 and Bax expression; up-regulates Bcl-2 expression; and possibly plays a protective role in diabetic retinopathy by reducing oxidative stress induced by high glucose and inhibiting cell damage and apoptosis." (PMID 35566359, 2022). "Overall, the network effects of CASP9, CELA2A, CELA2B and DANJC16 on type 2 diabetes, especially diabetic retinopathy, worth further investigations." (PMID 28511641, 2017).
E. coli infection (3 papers, 2019 to 2025). "Apoptotic markers caspase 3 and caspase 9 revealed increased expression due to E. coli infection, whereas LD4-PP treatment nullified the effect of infection." (PMID 41415272, 2025). "In response to E. coli infection, cleaved caspase-9 levels were significantly increased, indicating phagocytosis-induced cell death by apoptosis as it was expected." (PMID 32082070, 2019). "Therefore, we measured both cleaved caspase-9 and caspase-3 in response to E. coli infection and phagocytosis of E. coli and investigated whether AREG stimulation is capable of inhibiting the cleavage by preventing the formation of MAC via EGFR." (PMID 32082070, 2019).
Ewing sarcoma (3 papers, 2003 to 2016). A small round cell tumor that lacks morphologic, immunohistochemical, and electron microscopic evidence of neuroectodermal differentiation. "Treatment with viscum or viscumTT induced apoptosis in a concentration-dependent manner in primary Ewing sarcoma cells ex vivo, leading to mitochondrial membrane depolarization and CASP8 and CASP9 activation." (PMID 27589063, 2016). "SOX2 advanced Ewing’s sarcoma cell survival and proliferation by regulating p21, p27 and cyclin-E to facilitate G1/S phase transition and mediating caspase-3, PARP via both extrinsic (Fas and caspase-8) and intrinsic (caspase-9, Bad, Bcl-2 and XIAP) apoptotic pathways to restrain cell apoptotsis." (PMID 26969300, 2016).
fibrosarcoma (3 papers, 2015 to 2019). A malignant mesenchymal fibroblastic neoplasm affecting the soft tissue and bone. "The data suggests that 5-FU NPs demonstrate remarkable efficacy in up-regulation of caspase-9 and facilitating apoptosis of fibrosarcoma in mouse model." (PMID 31444363, 2019).
gallbladder carcinoma (3 papers, 2014 to 2022). "To investigate the molecular mechanism underlying the apoptotic effects of UA on gallbladder carcinoma cells, we assessed the expression of several apoptosis-related proteins, including PARP, caspase-3, caspase-9, cytochrome c, Bax and Bcl-2, by western blot analysis." (PMID 25383044, 2014).
glaucoma (3 papers, 2020 to 2022). Increased pressure in the eyeball due to obstruction of the outflow of aqueous humor. "Caspase-9 activation also occurs in retinal ganglion neurons in patients with type 2 diabetes and in patients with glaucoma." (PMID 34305609, 2021).
head and neck cancer (3 papers, 2012 to 2025). A primary or metastatic malignant neoplasm affecting the head and neck. "Procaspase-3 and procaspase-9 are cleaved into their active forms, cleaved caspase-3 and cleaved caspase-9, respectively, leading to apoptosis in several human cancers, including head and neck cancer." (PMID 40535821, 2025). "A previous study suggested that etoposide-induced apoptosis in head and neck carcinoma cellsis dependent on mitochondria-mediated caspase-9 activation." (PMID 23028682, 2012).